IGF1R (insulin like growth factor 1 receptor)
Diseases named in the same sentence as IGF1R in open-access papers (continued):
Sharing a sentence is not in itself a finding about the gene and the disease.
sarcoma (continued). "In general, the therapeutic benefits of IGF-1R inhibitors have been disappointing, but there have been some limited responses and instances of disease stabilization in patients with sarcomas." (PMID 24458261, 2014). "Clinical trials of IGF1R-inhibiting antibody therapies in patients with sarcomas, however, have returned mixed results: patients show variability in responsiveness to these therapies." (PMID 25170759, 2014). "The phase I study of everolimus and CP-751871, a fully human anti-IGF-1R mAb, achieved SD in patients with sarcoma and other solid tumors." (PMID 23755370, 2013). "Data from over 20 years ago demonstrated potential use for insulin-like growth factor (IGF) signaling modulators, specifically with IGF-1R antagonists, in a variety of pediatric and adolescent cancers, particularly in sarcomas." (PMID 23383402, 2013). "In this paper, we demonstrated that metformin was equally effective in sarcoma cells sensitive or resistant to different drugs, including conventional or anti-IGF1R agents." (PMID 24391834, 2013). "Based on the strong biological rational of inhibiting IGF-1R mediated signaling in sarcoma, many clinical trials were conducted or are ongoing in this patient population." (PMID 22415797, 2012). "A small number of clinical responses in patients with sarcomas have been reported across the different phase I clinical trials using IGF1R antibodies and have raised hope for the success of this therapeutic modality." (PMID 21437217, 2011). "IGF1R has been acknowledged as a biologically relevant target in pediatric sarcomas for some time, but it has been difficult to, target it therapeutically due to its similarity to the IR and the toxicities associated with nonspecific inhibition." (PMID 21437217, 2011). "There is a large amount of preclinical, clinical, and epidemiological data supporting targeting the IGF1R pathway in sarcomas, and specifically RMS." (PMID 21437217, 2011). "In recent years, several agents against IGF1R have entered clinical trials of various tumor types, including sarcomas and RMS." (PMID 21437217, 2011). "One IGF-1R inhibitor, CP751871, caused complete IGF-1R downregulation, suppressed AKT phosphorylation, and dramatically suppressed tumor-derived vascular endothelial growth factor (VEGF) in some sarcoma xenografts." (PMID 21197468, 2011). "Herein, we present the rationale for dual targeting of IGF-1R and other signaling molecules as an effective strategy to combat acquired drug resistance by carcinomas and sarcomas." (PMID 24212944, 2011). "Now is an exciting time to exploit additional novel therapeutics in sarcomas by optimizing the IGF1R blockade." (PMID 21052545, 2011). "Inhibition of IGF1R affects Ewing's sarcoma cell growth in vivo and seems to sensitize sarcoma cells to conventional agents by a synergistic interaction, suggesting a therapeutic combination approach." (PMID 21078151, 2010). "IGF1R signaling was blocked in many other types of sarcomas to explore its role in cell proliferation and survival in vitro, and tumor growth, invasion and metastasis in vivo in animal models." (PMID 21078151, 2010). "Promising results of anti-IGF1R therapy have also been reported on patients with sarcomas in phase-I studies." (PMID 20924377, 2010). "The mRNA levels of IGF1 and IGF2 were enhanced, but the expression of IGF1R was unaltered in sarcoma, indicating that tumor proliferation might be promoted by an increased effect of IGF1 and IGF2." (PMID 38338920, 2024). "Furthermore, the scientists discovered that IGF1R or ROR1 CAR-T cells were highly effective at inhibiting the growth of sarcoma in localized and disseminated sarcoma xenograft models which resulted in a prolonged survival rate." (PMID 36983330, 2023). "There is also evidence that nuclear IGF-1R associates with response to IGF-1R antibody therapy in patients with sarcoma, suggesting that nuclear IGF-1R may indicate dependence on the IGF axis." (PMID 33969359, 2021).
sarcoma (continued). "An siRNA-based screening identified RPS6 as an effector of IGF1R inhibition in sarcoma cells." (PMID 35008473, 2021). "In addition, the adoptive transfer of IGF1R-targeted CAR-T cells also displayed a prolonged survival benefit in a localized sarcoma model." (PMID 34503279, 2021). "In addition, IGF1R-targeted CAR-T cells have also resulted in the benefit of prolonged survival in a localized sarcoma model." (PMID 34566963, 2021). "Notably, a generalized IGF-IR signaling input in sarcoma progression was demonstrated by a recent meta-analysis correlating IGF-1R expression with poor outcomes regarding overall survival in sarcoma patients." (PMID 34069554, 2021). "Moreover, studies in sarcoma and neuroblastoma cell lines showed that sensitivity toward a specific tyrosine kinase inhibitor (BMS-536924) was associated with high basal IGF1R expression." (PMID 32391121, 2020). "Alternatively, overexpressed surface targets that drive sarcoma biology (i.e., insulin-like growth factor type 1 receptor (IGF1R), EGFR) may provide additional candidates for a cancer vaccine or T cell therapy (i.e., CAR T cell)." (PMID 31311607, 2019). "Exclusive nuclear IGF1R correlated with a better outcome in sarcoma patients treated with an IGF1R mAb, indicating that nuclear staining in the absence of cytoplasmic IGF1R may be a useful biomarker; however, this study had small numbers of patients." (PMID 31179642, 2019). "IGF1R is considered a very important element in the development of childhood sarcomas." (PMID 28793874, 2017). "Whereas the inhibition of tyrosine phosphorylation of PDGFR and ERBB family members was a common event in roneparstat-treated cells from the different sarcoma histotypes, the drug interference on the activation of other receptors (i.e. IGF1R, FGFR4) was found to occur in a cell line-specific way." (PMID 27374103, 2016). "For example, osteosarcoma and Ewing's sarcoma and a variety of other sarcomas over-express IGF1R." (PMID 27509178, 2016). "Likewise, the PAX3-FKHR fusion protein characteristic of alveolar rhabdomyosarcoma was shown to transactivate the IGF1R promoter in sarcoma-derived cell lines." (PMID 27285981, 2016). "While a randomized Phase II study testing the addition of the IGF1R mab ganitumab to chemotherapy in EWS is ongoing (NCT02306161), CAR T cells targeting IGF1R may be an alternative treatment for high risk patients with EWS and other sarcomas." (PMID 26173023, 2015). "To test our hypothesis, we first evaluated IGF1R surface expression in a panel of sarcoma cell lines using flow cytometry." (PMID 26173023, 2015). "Our data indicate that IGF1R and ROR1 CAR T cells could be used as a potential therapy for high risk sarcomas." (PMID 26173023, 2015). "Our data indicate that both IGF1R and ROR1 can be effectively targeted by SB modified CAR T cells and that such CAR T cells may be useful in the treatment of high risk sarcoma patients." (PMID 26173023, 2015). "IGF1R has been reported to be expressed in various hematologic and solid tumors including multiple myeloma, leukemia, lymphoma, breast, prostate, lung, colon, thyroid, renal, adrenal cancer, retinoblastoma, and sarcoma." (PMID 26173023, 2015). "IGF-1R is a transmembrane receptor highly expressed in many human cancers, including sarcomas." (PMID 25613038, 2015). "Note that most sarcoma cell lines appear to express low levels of IGF1R on the surface." (PMID 26173023, 2015). "This suggests that exclusive nuclear IGF-1R staining might serve as a predictive biomarker for sarcoma patients likely to benefit from IGF-1R mAb therapy." (PMID 26217584, 2015). "IGF1R signaling has been previously modulated in sarcoma in preclinical and clinical models." (PMID 23688189, 2013). "Overall, our findings suggest that IGF-1R as a therapeutic target in this sarcoma may require reevaluation." (PMID 23431249, 2013). "IGF-1R axis alteration were described in many sarcoma subtypes." (PMID 22415797, 2012).
sarcoma (continued). "Since more than fifty sarcomas subtypes exist, each clinically and molecularly distinct from one another and often driven by unique pathognomonic genomic translocations, the effects of IGF-1R signaling are naturally varied and subtype specific." (PMID 24212944, 2011). "It's still too early to predict from ongoing clinical trials which sarcoma subtypes will ultimately benefit the most from IGF-1R targeting, as unexpected clinical responses have occurred in several diverse subtypes (e.g., solitary fibrous tumors, liposarcoma, and others)." (PMID 24212944, 2011). "The IGF1R plays an important role in the growth and development of normal tissue as well as the initiation, maintenance, survival, progression, and metastasis of many sarcomas including EWS." (PMID 21052545, 2011). "Correlative lab and biomarker findings from anti-IGF1R studies may help illuminate the cell signaling and biology of sarcomas in general and EWS in particular." (PMID 21052545, 2011). "Therefore IGF1R has been investigated in cancer therapy and strategies for its inhibition in sarcoma have already been reported." (PMID 21078151, 2010). "Preclinical studies have also suggested a promising activity of CAR T cells targeting the type I insulin-like growth factor receptor (IGF1R) and the tyrosine–kinase-like orphan receptor 1 (ROR1), which are highly expressed in sarcoma cell lines." (PMID 37190214, 2023). "Generation and genetic characterization of novel patient-derived CIC-DUX4 sarcoma xenografts and cell lines successfully highlighted the importance of the insulin-like growth factor 1 (IGF1)/IGF1 receptor (IGF1R) pathway in this tumor." (PMID 36358827, 2022). "Among the SP1 downstream targets, that we found to be efficiently downregulated by MTM, there are some of the genes most commonly amplified/upregulated in sarcomas, such as C-MYC, VEGF or IGF1R." (PMID 33806182, 2021). "Anti-IGF-1R CAR T cells and anti-ROR1 CAR T cells derived from healthy donors showed cytotoxicity against IGF-1R positive and ROR1 positive sarcoma cell lines in vitro, respectively, and were able to release IFN-γ, TNF-α and IL-13 upon antigen stimulation." (PMID 33207697, 2020). "The authors designed IGF-1R-targeting CAR-T cells and revealed that they selectively exerted their cytotoxicity against sarcoma cells in localized and disseminated xenografts model and extended overall survival." (PMID 33511137, 2020). "Co-culture of PBMCs with IGF1R and ROR1 CAR T cells derived from a sarcoma patient and a healthy donor revealed a low level of recognition of PBMCs by IGF1R CAR T cells but not ROR1 CAR T cells compared to sarcoma cells." (PMID 26173023, 2015). "Altogether, these results demonstrate that SB engineered IGF1R and ROR1 CAR T cells derived from a sarcoma patient can suppress sarcoma growth in vivo." (PMID 26173023, 2015). "IGF1R and ROR1 CAR T cells generated from three sarcoma patients released significant amounts of IFN-γ in response to sarcoma stimulation." (PMID 26173023, 2015). "We demonstrated that Sleeping Beauty (SB) transposon-modified T cells with IGF1R- and ROR1-specific CARs were reactive against many types of sarcomas." (PMID 26173023, 2015). "IGF1R and ROR1 CAR T cells derived from eight healthy donors using the Sleeping Beauty (SB) transposon system were cytotoxic against sarcoma cells and produced high levels of IFN-γ, TNF-α and IL-13 in an antigen-specific manner." (PMID 26173023, 2015). "We also showed that adoptive transfer of IGF1R- and ROR1-specific CAR T cells from a sarcoma patient significantly reduced tumor growth in pre-established, systemic and localized sarcoma xenograft models." (PMID 26173023, 2015).
sarcoma (continued). "IGF1R CAR T cells produced higher amounts of IL-6 and IL-18 than ROR1 CAR T cells in response to certain sarcoma lines." (PMID 26173023, 2015). "IGF1R CAR T cells (IGZ) from those 4 donors were cytotoxic to Rh30 and SaOS2 sarcoma cells (vs K562, p = 0.0001)." (PMID 26173023, 2015). "Second, SB modified CAR T cells derived from healthy donors and sarcoma patients targeting IGF1R or ROR1 displayed a specific cytotoxicity and released predominantly IFN-γ, TNF-α and IL-13 cytokines against sarcomas in vitro." (PMID 26173023, 2015). "Altogether, these results firmly demonstrate that both IGF1R and ROR1 CAR T cells are cytotoxic to antigen+ sarcoma cells in vitro." (PMID 26173023, 2015). "These experiments demonstrate that SB-engineered IGF1R and ROR1 CAR T cells from a sarcoma patient can function as antitumor effector cells in vivo." (PMID 26173023, 2015). "Third, Both IGF1R and ROR1 CAR T cells derived from a sarcoma patient can significantly suppress sarcoma growth in both localized and disseminated pre-established sarcoma xenograft models." (PMID 26173023, 2015). "Similar levels of IGF1R or ROR1 CAR and GFP coexpression were observed in nucleofected PBMCs from two healthy donors and two sarcoma patients compared to SB modified T cells co-expressing CD19 CARs and CD20 as we previously reported (data not shown)." (PMID 26173023, 2015). "Infusion of IGF1R and ROR1 CAR T cells also prolonged animal survival in a localized sarcoma model using NOD/scid mice." (PMID 26173023, 2015). "Next, we determined if SB modified IGF1R and ROR1 CAR T cells kill sarcomas in an antigen-specific manner." (PMID 26173023, 2015). "A final auto-stimulatory circuit occurs via up-regulation of IGF-1R itself, as is the case of desmoplastic small round cell tumors (DSCRT), an even rarer sarcoma subtype the bares substantial molecular and clinical similarities to EWS." (PMID 24212944, 2011). "More recently, in a preliminary report of the SARC011, a phase II trial in multiple sarcoma types, described 3 objective radiological responses in patients with RMS treated with the anti-IGF1R antibody R1507." (PMID 21437217, 2011). "Several other targets of interest such as insulin-like growth factor receptor 1 (IGF-1R), receptor tyrosine kinase-like orphan receptor 1 (ROR1), and Ephrin type-A receptor 2 (EphA2) are overexpressed in various sarcomas and few CAR T-cell therapy clinical studies are currently ongoing." (PMID 40940995, 2025). "Also, the insulin receptor involves metabolic regulation and forms a hybrid receptor with IGF1R for IGF1, the latter together with IGF2, to promote the proliferation of sarcoma cells." (PMID 38338920, 2024). "The IGF‐1R/mTOR pathway is the most common abnormal activation of the growth factor signaling cascade, and IGF‐1 regulates osteogenesis and homeostasis, which plays an important role in the pathogenesis of sarcoma." (PMID 36807772, 2023). "Yet, targeted inhibition of IGF1R alone did not suffice to silence crucial downstream signaling nodes in these sarcomas in vitro." (PMID 32272784, 2020). "The IGF-1R phosphorylation state of sarcoma patients treated with IGF-1R Abs has not been reported in other studies, nor has pIGF-1R been linked to prognosis more generally." (PMID 32630797, 2020). "IGF-1R and tyrosine kinase-like orphan receptor 1 (ROR1) are highly expressed in ES cells, and the application of adoptive T-cell therapy using IGF-1R-CAR-T and ROR1-CAT-T cells derived from sarcoma patients significantly increases ES cell death and reduces tumor growth of sarcoma xenografts." (PMID 32754598, 2020). "Given that the AKT/mTOR pathway lies downstream of IGF-1/IGF-1R signaling and the success of combined mTOR/IGF-1R inhibition in sarcomas, future clinical trials could benefit from looking at a similar combined approach to chordoma management." (PMID 32733369, 2020).
sarcoma (continued). "IGF1R has been suggested as a driver of tumor growth in sarcomas, and ganitumab, an IGF1R antibody, is currently being studied in trials for metastatic EWS and advanced sarcomas." (PMID 31311607, 2019). "Here, we investigated CAR T-cell therapy targeting IGF1R and ROR1 in sarcomas." (PMID 26173023, 2015). "Moreover, adoptive transfer of IGF1R and ROR1 CAR T cells also demonstrated a prolonged survival benefit in a localized sarcoma model." (PMID 26173023, 2015). "IGF1R and ROR1 CAR T cells may represent a new treatment option for patients with metastatic or relapsed/refractory sarcomas." (PMID 26173023, 2015). "However, together with IGF1R it forms a hybrid receptor for IGF1, latter together with IGF2 is thought to have a key role in driving the proliferation and survival of sarcoma cells." (PMID 25496518, 2014). "Lack of correlation between IGF-1R and IR expression and sensitivity to metformin in pediatric sarcomas." (PMID 24391834, 2013). "Phase I and II studies of IGF1R antagonists figitumumab, cixutumumab, AMG479, R1507, and SCH 717454 either alone or in combination with other agents, are currently under clinical investigation for patients with sarcomas." (PMID 22665999, 2012). "Although IGF1R agents have the potential for cardiotoxicity, none of these antibodies have yet demonstrated cardiotoxicity, even in sarcoma patients who received prior anthracycline-based regimens." (PMID 21052545, 2011). "The introduction of humanized monoclonal antibodies that inhibit IGF1R in phase I and II clinical trials and the dramatic single-agent anti-IGF1R activity observed in refractory EWS patients provided the initial excitement in the sarcoma community." (PMID 21052545, 2011). "Here, using Ewing Sarcoma (EWS) as a tumor model, we demonstrate that the intracellular vesicular traffic regulatory protein EHD1 promotes tumorigenesis and metastasis by serving as a required element of IGF-1R traffic to enable IGF-1R-mediated oncogenic programs." (PMID 37474760, 2023). "Since lower concentrations of drug were needed to inhibit growth of the sarcoma cell lines with IGFR1 copy number amplications [see right panel that compares AUC of clofarabine in cell lines with IGF1R gene deletion (clofarabine nonsensitive) or amplification (clofarabine sensitive)]." (PMID 30704460, 2019). "Correlation analysis of CNVs from CCLE with drug-response data of CTRP in 27 sarcoma cell lines, 33 CNVs out of 63 genes correlated with either sensitivity or resistance to 17 chemotherapies from which actionable CNV signatures such as IGF1R, MYC, MAPK1, ATF1, and MDM2 were identified." (PMID 30704460, 2019). "A novel small molecule inhibitor of the IGF-1R/IR/ALK triad, GSK1838705A, has shown antitumor activity in human tumor models and should help elucidate the relationship of IGF-1R pathway activation in ALK-positive tumors noted within subtypes of NSCLC, lymphoma, and sarcoma." (PMID 24212944, 2011). "There are no doubts that IGF system is important for the pathogenesis and progression of sarcomas: cells produce ligands and express the receptors creating a complex network of autocrine stimulations that may sustain tumor growth based either on IGF1/IGF1R or IGF2/IR axis." (PMID 24391834, 2013). "In addition, both IGF1R and ROR1 CAR T cells but not mock T cells derived from 3 patients with sarcoma released significant amounts of IFN-γ in response to specific sarcoma antigen stimulation." (PMID 26173023, 2015).